PPARGC1B (PPARG coactivator 1 beta)
Diseases named in the same sentence as PPARGC1B in open-access papers (continued):
Sharing a sentence is not in itself a finding about the gene and the disease.
breast invasive carcinoma (1 paper, 2020). "In breast invasive carcinoma, particularly, PPARG and PPARGC1B were negatively correlated with tumor purity." (PMID 33029111, 2020).
fibrosis (1 paper, 2017). the formation of excess fibrous connective tissue in an organ or tissue in a reparative or reactive process. "Moreover, offspring of HFD dams had altered methylation patterns in DMRs of genes that play important roles in hepatic fibrosis and lipid accumulation, including Ppargc1β, Fgf21, Ephb2 and VWF." (PMID 28414763, 2017).
Glucose intolerance (1 paper, 2022). Glucose intolerance (GI) can be defined as dysglycemia that comprises both prediabetes and diabetes. "IPA suggested four upstream regulators that could be linked to glucose intolerance: interleukin 6 (IL6), tuberous sclerosis complex 2 (Tsc2), peroxisome proliferator-activated receptor gamma coactivator 1-beta (Ppargc1b), and lysine (K)-specific histone demethylase 1A (Kdm1a)." (PMID 35377872, 2022).
hyperreactivity (1 paper, 2013). "rs32588 is within the exon of peroxisome proliferator-activated receptor gamma, coactivator 1 beta (PPARGC1B), which was associated with airway hyperreactivity in asthmatic patients." (PMID 23527081, 2013).
hypospadias (1 paper, 2019). Hypospadias is the displacement of the urethral meatus on the ventrum of the penis. "Patient 7 presented five variants in five genes: EVC, MAML3, NOTCH2, PPARGC1B and WDR11; four of them associated with hypospadias or male gonadal development and one, MAML3, with female gonadal development." (PMID 31555317, 2019).
prostate carcinoma (1 paper, 2023). A carcinoma that arises from epithelial cells of the prostate gland. "Many of the immune response related (e.g., IRF8, JAK3, PTGER4, RELB, IFITM3) and part of the lipid metabolism related genes (e.g., NR1H4, PPARGC1B, PLIN1, HSD17B14) were identified to be adaptive which addressed their significance for prostate cancer." (PMID 36809527, 2023).
tumor (32 papers, 2012 to 2025). "The association of PPARGC1B (a PPARγ coactivator) with favorable prognosis suggests that enhancing lipid catabolism may counteract tumor growth, whereas PFKFB4-mediated pentose phosphate flux promotes lipogenesis, driving aggressiveness." (PMID 41364140, 2025). "For example, DLBCL-derived EVs promote M2 polarization of macrophages by increasing the expression of functional PPARG coactivator 1 beta (PGC-1β) protein, which in turn promotes tumor progression." (PMID 41551601, 2025). "We found a reduced expression of PPARGC1B and miR-378 in tumour samples as compared to tumour adjacent normal tissue." (PMID 38203358, 2023). "We used TNMplot to determine the expression of PPARGC1B and miR-378 in normal and tumour tissue samples of the breast." (PMID 38203358, 2023). "Some of the identified prognostic DE RBPs have been reported associated with tumor progression, such as RBM47, LUZP4, AFF3, PPARGC1A, PPARGC1B, PABPC3, and PNLDC1." (PMID 33224957, 2020). "Significant differences were found between PPARGC1A and PPARGC1B towards their relationship with tumor purity." (PMID 33029111, 2020). "While it remained unchanged in the gastrocnemius tissue, Ppargc1b mRNA levels were significantly decreased in quadriceps tissue of tumor-bearing MCK-PGC-1αmice." (PMID 22428048, 2012). "We performed multidimensional analyses on PPARA, PPARG, PPARD, PPARGC1A, and PPARGC1B, including differential expression analysis in pan-cancer, immune subtype analysis, clinical analysis, tumor purity analysis, stemness correlation analysis, and drug responses." (PMID 33029111, 2020). "Importantly, decreased levels of mitophagy-related BNIP3L and PINK1, as well as increased levels of mitochondrial biogenesis related genes PPARGC1A and PPARGC1B were found in the basal-like tumor samples when compared to the Luminal A subtype." (PMID 31231612, 2019). "We found that upon separating the tumours by stage (Bittner dataset GSE2109), the expression of PPARGC1B showed a significant downregulation with increasing tumour stage." (PMID 38203358, 2023). "The higher expression of PPARGC1A was correlated with high tumor purity in CHOL, GBM, KIRC, KIRP, and THCA, while with low stromal scores of BLCA, HNSC, LUSC, and TGCT, which was the opposite to the pattern of PPARGC1B." (PMID 33029111, 2020). "Moreover, according to the C1-C6 immune subtypes previously identified by investigators, we classified tumor samples by representative immune signatures and examined the RNA-seq level of PPARA, PPARD, PPARG, PPARGC1A, and PPARGC1B from C1 to C6, which were all seen to have differential expressions." (PMID 33029111, 2020).
cancer (26 papers, 2011 to 2025). A tumor composed of atypical neoplastic, often pleomorphic cells that invade other tissues. "PGC1β, which has been reported to exert an important role in cancer metabolism and progression, is encoded by the gene PPARGC1β." (PMID 33777130, 2021). "The expression patterns of PPARA (p < 0.001), PPARD (p < 0.001), PPARG (p < 0.001), PPARGC1A (p < 0.001), and PPARGC1B (p < 0.001) varied in 6 immune subtypes in pan-cancers." (PMID 33029111, 2020). "In this study, we analyzed the expression signatures of PPARA, PPARD, PPARG, PPARGC1AA, and PPARGC1B in pan-cancer." (PMID 33029111, 2020). "PPARGC1B plays a critical role in mitochondrial biogenesis, as identified in cancer studies." (PMID 37628680, 2023). "The PPI network identified that ESRRG was significantly related to 20 genes, including PPARGC1A, PPARGC1B, MED1, CREBCF and so on, 6 of which were confirmed to be positively correlated with ESRRG expression by the XenaShiny TCGA Association Analysis module for single cancer." (PMID 40356747, 2025). "Lastly, the synergism demonstrated in the present study also suggests that disrupting the interaction between an ER co-activator - such as PPARGC1B - and ERα, or blocking their mutual activation, may represent a sensitive and leveraged strategy for cancer prevention." (PMID 21269472, 2011). "Further investigations are required to figure out the potentials of PPARs and their coactivators as drug targets for cancer, which makes our study even more important in the contribution to the expression signature analysis of PPARA, PPARD, PPARG, PPARGC1A, and PPARGC1B." (PMID 33029111, 2020).
infection (19 papers, 2008 to 2024). The state of being infected such as from the introduction of a foreign agent such as serum, vaccine, antigenic substance or organism. "Contrary to ZFP36L1 expression, levamisole‐induced down‐regulation of PPARGC1B was completely compensated by PPARGC1B up‐regulation resulted from lenti‐shZFP36L1 infection (d vs c, b vs c)." (PMID 29993187, 2018). "We found an early up-regulation of Ppargc1a and Ppargc1b post-infection (at 6 h) in WT mice, but the expression of both genes was concordantly dysregulated in TLR2−/− mice (no increase at 6 h) and in TLR4−/− mice (amplified at 6 h)." (PMID 20657826, 2010). "qRT‐PCR analysis revealed that lenti‐shPPARGC1B infection significantly decreased PPARGC1B mRNA expression, which resulted in significant down‐regulation of the mRNA levels of the adipogenic differentiation markers (PPARγ, PLIN1, LPL and FABP4) as compared with the lenti‐ctrl infection." (PMID 29993187, 2018).
metabolic disorders (9 papers, 2013 to 2025). "PPARA, PPARGC1A, and PPARGC1B, which are involved in the fatty acid oxidation of PLN-KO hiPSC-CMs, began to decline at day 30, while genes involved in glucose utilization, such as GNPNAT1, PGM3, and GFPT1, were upregulated, indicating that energy metabolism disorders began to occur." (PMID 35334215, 2022).
PPARGC1B also shares sentences with these, for which no sentence is quoted: hepatocellular carcinoma (9 papers); breast tumor (6); cardiac hypertrophy (5); hyperlipidemia (5); renal carcinoma (4); colorectal cancer (3); Ventricular arrhythmia (3); colitis (2); diabetic cardiomyopathy (2); dilated cardiomyopathy (2); Hepatic fibrosis (2); Hyperglycemia (2); liver cancer (2); lymphoma (2); metabolic syndrome (2); myopathy (2); peritonitis (2); schizophrenia (2); viral infection (2); Acute hepatic failure (1); acute liver failure (1); adenocarcinoma (1); alcohol (1); alcoholic liver diseases (1); amyotrophic lateral sclerosis (1); anemia (1); aplastic anaemia (1); arrhythmogenic right ventricular cardiomyopathy (1); Arthritis (1); atherosclerosis (1).
A further 55 diseases each share a sentence with PPARGC1B in 1 paper.